PALB2 (partner and localizer of BRCA2)
Diseases named in the same sentence as PALB2 in open-access papers (continued):
Sharing a sentence is not in itself a finding about the gene and the disease.
hematologic neoplasms (1 paper, 2025).
PALB2 also shares sentences with these, for which no sentence is quoted: colon cancer (8 papers); hereditary breast and ovarian cancer syndrome (8); breast and (7); Li-Fraumeni syndrome (7); metastatic disease (5); hereditary nonpolyposis colorectal cancer (4); childhood cancer (3); ductal carcinoma in situ (3); glioma (3); hepatocellular carcinoma (3); hereditary colorectal cancer (3); hereditary pancreatitis (3); Pancreatic cysts (3); skin cancer (3); basal cell nevus syndromes (2); chronic pancreatitis (2); familial atypical multiple mole melanoma syndrome (2); Hypertension (2); metastatic cancer (2); neurofibromatosis type 1 (2); Obesity (2); renal cell carcinoma (2); acinar cell carcinoma (1); acute lymphoblastic leukemia (1); arrhythmogenic right ventricular dysplasia type 5 (1); asthma (1); astrocytoma (1); autosomal recessive disease (1); basal cell carcinoma (1); Beckwith-Wiedemann syndrome (1).
A further 70 diseases each share a sentence with PALB2 in 1 paper.